PTPN1 (protein tyrosine phosphatase non-receptor type 1)
Diseases named in the same sentence as PTPN1 in open-access papers (continued):
Sharing a sentence is not in itself a finding about the gene and the disease.
melanoma (19 papers, 2014 to 2024). A malignant, usually aggressive tumor composed of atypical, neoplastic melanocytes. "In the GSE91061 cohort, melanoma patients with low PTPN1 expression showed better OS than those with high PTPN1 expression." (PMID 37936713, 2023). "In melanoma, PTPN1 promotes melanoma progression by activating the Src signaling pathway through dephosphorylating the Tyr530 site of Src as well as by enhancing the Erk1/2 signaling pathway, respectively." (PMID 35957898, 2022). "In melanoma HDAC6, via the tyrosine phosphatase PTPN1 and enhanced ERK1/2 activity, has been proposed to enhance proliferation." (PMID 33898322, 2021). "HDAC6 binds to Tyrosine-protein phosphatase non-receptor type 1 (PTPN1), activates extracellular signal-regulated kinase 1/2 (ERK1/2), inhibits apoptosis, and promotes melanoma cell proliferation." (PMID 32626712, 2020). "To test whether PTPN1 and SOCS3 were required, we treated melanoma cells with SAHA and phosphatase inhibitors for 24 hours." (PMID 33158915, 2020).
Alzheimer disease (18 papers, 2011 to 2025). A progressive, neurodegenerative disease characterized by loss of function and death of nerve cells in several areas of the brain leading to loss of cognitive function such as memory and language. "Additional connection that the PTPN1 gene has to healthy ageing is its association with Alzheimer’s disease." (PMID 36735720, 2023). "Moreover, based on the PPI network, PTPN1 has direct interactions with GSK3B, PIK3R1, and CAPN1 in the Alzheimer’s disease pathway." (PMID 38612872, 2024).
ovarian cancer (18 papers, 2003 to 2024). A primary or metastatic malignant neoplasm involving the ovary. "PTPN1 and PTPN6 are highly expressed in ovarian cancer cell lines, in which PTPN1 accelerates ovarian cancer progression in a c-Jun N-terminal kinase (JNK)-dependent mechanism." (PMID 35957898, 2022). "Amplification of 20q13 may be particularly heterogeneous as AURKA, TGIF2, PTPN1 and ZNF217, and ADRM1, and other genes, have been cited as drivers of 20q13 amplification in ovarian cancer." (PMID 19419571, 2009).
gastric cancer (17 papers, 2018 to 2024). A primary or metastatic malignant neoplasm involving the stomach. "Reports have shown that high PTPN1 expression is associated with poor OS in patients with colorectal, pancreatic, and gastric cancers." (PMID 37936713, 2023). "High expression of PTPN1 is strongly associated with poor prognosis in gastric cancer." (PMID 32226775, 2020). "We found that PTPN1 overexpression was significantly associated with poor prognosis in ovarian (OS), lung (OS, FP, and PPS), and gastric cancers (OS)." (PMID 37936713, 2023). "PTPN1 significantly promotes gastric cancer (GC) cell proliferation in vitro and tumor growth in vivo by regulating Src-related signaling pathways, such as the Src/Ras/MAPK and Src/PI3K/AKT pathways." (PMID 35957898, 2022). "Furthermore, PTPN1 is implicated in the poor prognosis of gastric cancer, and PTPN2 is linked to the incidence of gastric cancer." (PMID 35957898, 2022). "In contrast, increased PTPN1 expression was related to significantly better prognosis in breast (OS, DMSF, PPS, and RFS), ovarian (PFS), and gastric cancers (PPS)." (PMID 37936713, 2023).
Hepatic steatosis (17 papers, 2012 to 2025). Steatosis is a term used to denote lipid accumulation within hepatocytes. "Furthermore, the upregulation of Ptpn1 encoding PTP1B may have influenced liver steatosis." (PMID 39600697, 2024). "A study revealed that by inhibiting Ptpn1 expression and promoting phosphorylation of insulin receptor, microRNA-206 impaired hepatic lipogenesis and exerted the beneficial effect of preventing hepatic steatosis." (PMID 37033250, 2023).
hepatocellular carcinoma (17 papers, 2016 to 2025). A malignant tumor that arises from hepatocytes. "However, high PTPN1 expression in hepatocellular carcinoma was significantly associated with good disease-free survival (DFS) and OS." (PMID 37936713, 2023). "We made several novel predictions, including that CDK1 and PTPN1 knockdown would be more effective in males with hepatocellular carcinoma, and SMAD3 and HSPA4 knockdown would be more effective in females with head and neck squamous cell carcinoma." (PMID 26755347, 2016). "In hepatocellular carcinoma, miR-122 and miR-206 target the 3’ untranslated region (3’ UTR) of PTPN1 mRNA and induce its degradation, while miR-125a-5p suppresses PTPN1 expression via the MAPK signaling pathway, both of which ultimately alleviated the progression of hepatocellular carcinoma." (PMID 35957898, 2022).
endothelial dysfunction (16 papers, 2013 to 2024). In vascular diseases, endothelial dysfunction is a systemic pathological state of the endothelium (the inner lining of blood vessels) and can be broadly defined as an imbalance between vasodilating and vasoconstricting substances produced by (or acting on) the endothelium. "In summary, we find PTPN1 expression is downregulated in the whole blood of PAH patients and PAECs exposed to hypoxia and that PTPN1 downregulation is associated with endothelial dysfunction in PAECs." (PMID 36672250, 2023). "We found PTPN1 as a novel modifier of BMPR2 signaling and showed that PTPN1 is decreased in the blood of PAH patients and PTPN1 deficiency is associated with induction of markers of endothelial dysfunction." (PMID 36672250, 2023). "We find that PTPN1 deficiency induces endothelial dysfunction by reducing proliferation, causing apoptosis and reducing tube formation of PAECs, all features linked to the development of PAH." (PMID 36672250, 2023). "We identified PTPN1 as a novel regulator of BMPR2 signaling in PAECs, which is downregulated in the blood of PAH patients, and documented that downregulation of PTPN1 is linked to endothelial dysfunction in PAECs." (PMID 36672250, 2023). "Additionally, PTPN1 and ATF6 expressions were correlated with ET1 which codes for a protein associated with septic endothelial dysfunction." (PMID 31737637, 2019). "As endothelial dysfunction plays an important role in PH pathogenesis and as the BMPR2 receptor is highly expressed in endothelial cells, we aimed to investigate the role of PTPN1 in modulating BMPR2 signaling and its effect on PAEC function in PAH." (PMID 36672250, 2023). "Quantitative PCR (performed from whole blood) evaluated the expression of genes coding for PTP1B (PTPN1) and key elements of ERS (GRP78, ATF6, CHOP) or for endothelial dysfunction-related markers (ICAM1 and ET1)." (PMID 31737637, 2019). "As endothelial dysfunction and perivascular inflammation are key players in PAH pathobiology, maintaining adequate PTPN1 levels could be significant for pulmonary vascular remodeling in PAH." (PMID 36672250, 2023). "There is no work studying the link between ET1 and PTP1B but, more than a direct link between these two markers, since ET1 is a marker of septic endothelial lesion, it is likely that the observed correlation could reflect the relationship between PTPN1 expression and septic endothelial dysfunction." (PMID 31737637, 2019).
Sepsis (14 papers, 2015 to 2025). Sepsis is defined as life-threatening organ dysfunction caused by a dysregulated host response to infection. "Notably, these DEPs including Fads2, Fgb, Cypla2, Cyp2e1, Cfb, Serping1, Fgg, Etnppl, Agt, Hsd3b5, Gnmt, A2m, Pck1, Stat3, Ptpn1, Scd1, Slc2a1, and Uox were key genes in liver sepsis, which maybe associated with inflammation in sepsis." (PMID 37255592, 2023). "Similarly to the rise in PTPN1 observed in septic foals in the study presented here, murine studies have demonstrated a similar pattern of a progressive increase in PTP1B levels in rat brains following the induction of sepsis." (PMID 40867920, 2025). "The levels of CLU, BCL2L1, USP14, PTPN1, OPA1, and CREB3 were elevated during sepsis and demonstrated a positive correlation with sepsis score." (PMID 40867920, 2025). "In regard to recent literature, our finding that PTPN1 and UPR genes are expressed in the plasma of patients with septic shock and that their expression shows significant variations suggests that these components may be involved in the pathophysiology of sepsis." (PMID 31737637, 2019).
glioma (13 papers, 2008 to 2023). A benign or malignant brain and spinal cord tumor that arises from glial cells (astrocytes, oligodendrocytes, ependymal cells). "Subsequently, the effects of miR-542-5p on RISC and proliferation associated gene AGO2 and PTPN1 were evaluated in glioma cells." (PMID 31015365, 2019). "Defuse glioma patients with PTPN1, and AGO2 mutation showed worse overall survival both in the overall group (p = 3.86 × 10−8) and disease-free/progression-free group (P=2.85 × 10−5), indicating that PTPN1 and AGO2 may play important roles in diffuse glioma and were related to survival rate." (PMID 31015365, 2019). "Mechanistically, PTPN1 promotes glioma progression through activation of MAPK/Erk and PI3K/AKT pathways as well as IL-13-mediated adhesion, migration and invasion of IL13Rα2-expressing cancer cells." (PMID 35957898, 2022). "Another study has demonstrated glioma progression by upregulation of protein tyrosine phosphatase 1B (PTPN1) via activating the MAPK/ERK and PI3K/AKT pathways." (PMID 34439380, 2021). "PTPN1 has been reported to strengthen the progression of glioma by activating the MAPK/ERK and PI3K/AKT pathways." (PMID 34026649, 2021). "The results suggested that miR-542-5p inhibitor transfection with pristimerin treatment enhance expression of AGO2 and decrease expression of PTPN1 significantly, which mean that pristimerin and miR-542-5p silence had the synergistic effect in glioma cells." (PMID 31015365, 2019). "Results indicated that post-treatment with pristimerin and miR-542-5p silence had profoundly the same effect, elevated AGO2 and decreased PTPN1, which might be related with cell proliferation, lead to glioma progression." (PMID 31015365, 2019). "In addition, we observed that low-dose pristimerin inhibited the viability of glioma cells, while miR-542-5p in vitro; and reduced PTPN1 expression." (PMID 31015365, 2019). "Additionally, the immunofluorescence staining images of two cancer cell lines (human epidermoid carcinoma cell line A-431 and malignant human glioma cell lines U-251) obtained from the HPA database showed that PTPN1 was mainly localized in the endoplasmic reticulum (ER)." (PMID 37936713, 2023). "Our findings suggest that in the presence of a low-concentration of pristimerin, cell viability and expression of PTPN1 were significantly down-regulated, while pristimerin levels were elevated; and higher concentration of pristimerin could induce apoptosis in glioma cells." (PMID 31015365, 2019). "In conclusion, pristimerin inhibited glioma progression through AGO2 and PTPN1 expression via a canonical miRNA-mediated mechanism." (PMID 31015365, 2019). "In summary, the present study revealed that pristimerin participated in the proliferation, apoptosis of glioma cells and demonstrated that AGO2 and PTPN1 were partially responsible for the miR-542-5p induced inhibition of cell proliferation." (PMID 31015365, 2019). "PTPN1 and PTPN2 can be used as predictors of poor prognosis in glioma patients." (PMID 35957898, 2022). "Inhibited Glioma progression by targeting AGO2 and PTPN1 expression via miR-542-5p." (PMID 34026649, 2021). "Furthermore, miR-542-5p silence with siRNA in glioma cells lead to the elevation in AGO2, and decreased PTPN1 level." (PMID 31015365, 2019). "Furthermore, we proved that in low concentration, pristimerin inhibited the viability of glioma cells through AGO2, and suppressed expression PTPN1 via a canonical miRNA-mediated silencing mechanism, while in high concentration, pristimerin induced apoptosis." (PMID 31015365, 2019). "The glioma cells were transfection of miR-542-5p inhibitor and control for 48 h, and treated with or without pristimerin (1 μM) for 24 h, then qRT-PCR was performed to determine the expression of AGO2 and PTPN1." (PMID 31015365, 2019).
atherosclerosis (12 papers, 2015 to 2024). A disease characterized by the build-up of fatty material and calcium deposition in the arterial wall resulting in partial or complete occlusion of the arterial lumen. "The potential mechanisms were found to be mainly involved in phosphoinositide 3-kinase (PI3K)-Akt, JAK2, MAPK, protein tyrosine phosphatase non-receptor type 1 (PTPN1) signaling pathway, neuroactive ligand-receptor interaction, as well as fluid shear stress and atherosclerosis." (PMID 37007031, 2023).
glioblastoma (11 papers, 2020 to 2026). The most malignant astrocytic tumor (WHO grade IV). "Importantly, dual inhibition of PTPN1/N2 markedly enhances the cytolytic activity of cord blood NK cells against patient-derived glioblastoma cells, highlighting the potential of this approach for future therapeutic applications." (PMID 41986797, 2026). "Moreover, it has been shown that pristimerin, a natural-occurring quinone methide triterpenoid with anticancer effects, inhibits glioblastoma progression by targeting two receptors, the protein tyrosine phosphatase, non-receptor type 1 (PTPN1), and Argonaute 2 (AGO2) via miR-542-5p." (PMID 38730608, 2024).
lung carcinoma (10 papers, 2018 to 2023). "Although PTPN1 has been shown to play a certain role in promoting lung cancer, this conclusion is contrary to the existing prediction of bioinformation and experimental results, so we reverified the biological effect of PTPN1." (PMID 32395869, 2020). "PTPN1 (degree = 44), a unique target of LGT has been proved to promote the proliferation and metastasis of NSCLC and high expression in lung cancer tissues." (PMID 36339610, 2022). "Here, we used two different comprehensive bioinformatics analysis and revealed protein tyrosine phosphatase non-receptor type (PTPN) family genes, especially PTPN1 and PTPN22, were downregulated in lung cancer tissue in comparison with normal samples." (PMID 36556168, 2022).
Hypertension (9 papers, 2006 to 2024). The presence of chronic increased pressure in the systemic arterial system. "According to studies, PTPN1 gene variants may have a role in the emergence of hypertension." (PMID 37571339, 2023). "Numerous genes, including PTPN1 and NOS2, have been linked to the emergence of hypertension in leishmaniasis patients." (PMID 37571339, 2023). "Previous reports describe a link between PTPN1 SNPs and systemic hypertension." (PMID 36672250, 2023).
breast tumor (8 papers, 2016 to 2021). "This miRNA was also secreted by hypoxic breast tumour cells to the neighbouring TME, including endothelial cells, where it targeted vascular remodelling target genes, such as ephrin A3 and PTP1B (protein tyrosine phosphatase non-receptor type 1), resulting in promoted angiogenesis." (PMID 34064331, 2021).
esophageal cancer (8 papers, 2020 to 2023). A primary or metastatic malignant neoplasm involving the esophagus. "In contrast, PTPN1 was found to be a tumor suppressor in B cell lymphoma and esophageal cancer." (PMID 37936713, 2023). "Interestingly, PTPN1 expression is implicated in the incidence of esophageal cancer, while PTPN6 is down-regulated in esophageal cancer and PTPN12 is a favorable prognostic biomarker for patients with esophageal squamous cell carcinoma." (PMID 35957898, 2022). "For esophageal carcinoma (ESCA), PTPN1 and PTPN12 levels were correlated with incidence; PTPN20 was associated with poor prognosis." (PMID 32536826, 2020).
steatosis (8 papers, 2020 to 2024). Increased lipid within the cytoplasm of cells. "In addition, one study of cellular stress reported that ER stress induces the production of ROS and expression of PTPN1, an enzyme associated with ER stress, apoptosis, and steatosis." (PMID 33477489, 2021). "Farrerol treatment significantly restored the dephosphorylation of INSR by targeting PTPN1 and alleviated the steatosis of HepG2 cells by inhibiting the PI3K/AKT signalling pathway." (PMID 39289804, 2024).
lymphoma (7 papers, 2019 to 2022). A malignant (clonal) proliferation of B- lymphocytes or T- lymphocytes which involves the lymph nodes, bone marrow and/or extranodal sites. "PTPN1 mutations were present in 3% of breast implant-associated lymphomas, and this mutation not only activated the JAK/STAT signaling pathway, but also caused loss of function in epigenetic regulatory regions." (PMID 36618415, 2022).
non-small cell lung carcinoma (7 papers, 2017 to 2025). A group of at least three distinct histological types of lung cancer, including non-small cell squamous cell carcinoma, adenocarcinoma, and large cell carcinoma. "Remarkably, phosphatases can influence the response to TKI treatment as reported for PTPN1 (PTP1B), PTPN6 (SHP1) and PTPRC (CD45) for BCR-ABL TKIs treatment in chronic myeloid leukemia or for PTPN11 (SHP2) for acquired resistance to ALK-TKIs in ALK-rearranged non-small cell lung cancer (NSCLC)." (PMID 36698412, 2022).
bladder cancer (6 papers, 2021 to 2026). "Conversely, by targeting PTPN1, a tumor suppressor in bladder cancer, the miR-130 family (miR-130b, miR-301a, and miR-301b) contributes to cancer development." (PMID 35957898, 2022). "In bladder cancer, PTPN1 and PTPN12 function as tumor suppressors to attenuate the growth, invasion and migration of cancer cells." (PMID 35957898, 2022). "PTPN1 knockdown led to increased tumor properties (cell growth, invasion, and migration) and increased pSrcTyr416 expression in bladder cancer cells, suggesting that the miR-130 family upregulates multiple RTK signaling by targeting PTPN1 and subsequent Src activation in bladder cancer." (PMID 33947152, 2021).
Hodgkins lymphoma (6 papers, 2010 to 2023). A heterogeneous group of malignant lymphoid neoplasms of B-cell origin characterized histologically by the presence of Hodgkin and Reed-Sternberg (HRS) cells in the vast majority of cases. "In classical Hodgkin’s lymphoma, the PTPN1 splice variant was a positive adjustment factor for the JAK/STAT signal pathway." (PMID 36618415, 2022). "PTPN1 splice variants could up-regulated JAK/STAT activity in classic Hodgkin lymphoma cells, accelerated tumor cell proliferation, and reduced the toxicity effect of chemotherapy drugs such as gessabine and oroposide." (PMID 36618415, 2022). "A similar PTPN1-regulated mechanism was also observed in lymphoid malignancies and Hodgkin lymphoma." (PMID 36741874, 2023). "Recently, recurrent mutations in the PTPN1 gene encoding the human protein tyrosine phosphatase 1B (PTP1B) were reported in PMBCL and Hodgkin lymphoma, thus supporting previous evidence of the involvement of the PTP1B enzyme in lymphomagenesis." (PMID 35806064, 2022). "Loss of PTPN1 function through mutation has been shown to result in JAK/STAT activation in primary mediastinal B-cell lymphoma and Hodgkin lymphoma." (PMID 30546832, 2018). "Here we analyze the 3D telomere dynamics by Q-FISH in the novel Hodgkin cell line U-HO1 and its non-receptor protein-tyrosine phosphatase N1 (PTPN1) stable transfectant U-HO1-PTPN1, derived from a primary refractory Hodgkin's lymphoma." (PMID 21144060, 2010).
pancreatic cancer (6 papers, 2019 to 2023). "In pancreatic cancer, PTP1B—the protein encoded by the PTPN1 gene—was significantly overexpressed and was found to be associated with distant metastasis and tumor staging." (PMID 36012311, 2022). "For example, in colorectal, prostate, gastric, and pancreatic cancers, PTPN1 may act as a tumor promoter." (PMID 37936713, 2023).